AURKA (aurora kinase A)
Diseases named in the same sentence as AURKA in open-access papers (continued):
Sharing a sentence is not in itself a finding about the gene and the disease.
cholangiocarcinoma (3 papers, 2020 to 2025). A carcinoma that arises from the intrahepatic biliary tree (intrahepatic cholangiocarcinoma) or from the junction, or adjacent to the junction, of the right and left hepatic ducts (hilar cholangiocarcinoma). "Our data demonstrate that AURKA was highly expressed and associated with poor prognosis in cholangiocarcinoma." (PMID 32127951, 2020). "High AURKA mRNA expression was associated with poor survival in cholangiocarcinoma patients within different datasets." (PMID 32127951, 2020). "Furthermore, we analyzed the association of AURKA mRNA expression with cholangiocarcinoma outcomes in different cohorts using the mean AURKA expression value as a cut-off." (PMID 32127951, 2020). "Patients with higher AURKA mRNA levels in cholangiocarcinoma tumors showed significantly shorter overall survival time than those with lower levels of AURKA (P=0.0232)." (PMID 32127951, 2020). "Collectively, these data demonstrated that AURKA played a tumor promoting role in cholangiocarcinoma by regulating cell cycle and apoptosis." (PMID 32127951, 2020). "AURKA specific inhibitor Alisertib, inhibited cell growth, induced cell cycle arrest in G2/M phase, and promoted apoptosis in cholangiocarcinoma cell lines." (PMID 32127951, 2020). "We depleted AURKA to further elucidate Aurora kinase A is responsible for the cell proliferation of cholangiocarcinoma cells." (PMID 32127951, 2020). "In this study, we found that AURKA was highly expressed in cholangiocarcinoma and high AURKA expression was a good predictor of poor prognosis in cholangiocarcinoma." (PMID 32127951, 2020). "Cholangiocarcinoma cell lines exhibited different sensitivity to AURKA inhibition with IC50 values ranging from 38.4 nM to 303.1 nM." (PMID 32127951, 2020). "In the Copenhagen cohort (GSE26566), AURKA mRNA expression also correlated with cholangiocarcinoma overall survival time." (PMID 32127951, 2020). "SiRNA mediated suppression of AURKA were conducted in five cholangiocarcinoma cell lines and resulted in prominent reduction of protein expression at 48 hours post transfection." (PMID 32127951, 2020). "Taken together, our results showed that AURKA silencing by siRNA is sufficient to recapitulate the oncosuppressive effects of AURKA chemical inhibition on cholangiocarcinoma cells." (PMID 32127951, 2020). "Components of the mitotic spindle checkpoint, including AURKA, were broadly dysregulated in human cholangiocarcinoma patients using The Cancer Genome Atlas (TCGA) or Gene Expression Omnibus (GEO) datasets." (PMID 32127951, 2020). "AURKA inhibition is attractive in cholangiocarcinoma as it has been shown to interact with and control a variety of proteins that play key roles in cholangiocarcinoma pathogenesis such as STAT3 36 and Mcl-122." (PMID 32127951, 2020). "Material and methods: Different public datasets were analyzed to examine the expression of 76 selected mitotic spindle checkpoint genes including Aurora Kinase A (AURKA) in cholangiocarcinoma." (PMID 32127951, 2020). "Furthermore, siRNA mediated silencing of AURKA was used to verify the function of AURKA in cholangiocarcinoma." (PMID 32127951, 2020). "Considering the lack of established targeted therapeutics against cholangiocarcinoma, we propose that AURKA may be a potential prognostic marker and effective therapeutic target for cholangiocarcinoma." (PMID 32127951, 2020). "Our results support that AURKA sustains proliferation in cholangiocarcinoma." (PMID 32127951, 2020). "We hypothesized that this can be exploited therapeutically with AURKA inhibition, and we tested the antitumor activity of the selective AURKA inhibitor Alisertib in vitro in cholangiocarcinoma cell lines and in vivo in a mouse xenograft model." (PMID 32127951, 2020). "Furthermore, inhibition of AURKA using a highly specific small inhibitor Alisertib has proven here to be promising in targeting cholangiocarcinoma." (PMID 32127951, 2020).
cholangiocarcinoma (continued). "Next, we evaluated the impact of the AURKA inhibitor on cholangiocarcinoma cells in vitro." (PMID 32127951, 2020). "Notably, both TPX2 and PLK1 were among the top 20 correlated genes with AURKA in the TCGA dataset of cholangiocarcinoma based on Person correlation analysis." (PMID 32127951, 2020). "To determine whether AURKA may represent an appropriate therapeutic target in cholangiocarcinoma, we initially screened a panel of cholangiocarcinoma cell lines with Alisertib, a highly selective AURKA inhibitor." (PMID 32127951, 2020). "We sought to confirm the co-expression of TPX2, PLK1 and AURKA in cholangiocarcinoma datasets." (PMID 32127951, 2020). "Therefore, both in vitro and in vivo results support AURKA might be an effective therapeutic target in cholangiocarcinoma." (PMID 32127951, 2020). "In cholangiocarcinoma, the TF FOSL1 modulates AURKA expression, influencing cell proliferation and tumor growth." (PMID 40746357, 2025). "These are two well-established co-factors of AURKA in various cell lineages but not been reported in cholangiocarcinoma." (PMID 32127951, 2020). "The negative prognostic role of AURKA in cholangiocarcinoma was solid as it was validated in three different cholangiocarcinoma cohorts." (PMID 32127951, 2020). "AURKA mRNA was markedly higher in the cholangiocarcinoma compared to that in the normal bile ducts or surrounding normal livers in all three datasets." (PMID 32127951, 2020). "Collectively, these data indicate that highly expressed AURKA may be a negative prognostic factor in cholangiocarcinoma." (PMID 32127951, 2020). "We also found that highly expressed AURKA was a negative prognostic marker of cholangiocarcinoma." (PMID 32127951, 2020). "However, no study specifically investigates the role and function of AURKA in cholangiocarcinoma." (PMID 32127951, 2020).
colorectal tumors (3 papers, 2012 to 2020). "For example high level gain was observed at 20q where AURKA is located, frequent gain at 16p (PLK1), and loss at 4q (MAP9) in a number of colorectal tumors." (PMID 24876664, 2014). "We show here that, in colorectal tumors, MAP9 is strongly underexpressed whereas AURKA and PLK1 are overexpressed." (PMID 24876664, 2014). "In parallel, GEO data set analyses (GDS 2947) of colorectal tumors and adjacent normal tissue show downregulation of MAP9 and upregulation of AURKA and PLK1, with values that are similar to what we observed in this study." (PMID 24876664, 2014).
COVID-19 (3 papers, 2022 to 2024). A disease caused by infection with severe acute respiratory syndrome coronavirus 2. "The network pharmacology analysis identified seven core targets (namely, AURKA, CDK1, CCNB1, CCNB2, CCNE1, CCNE2, and TTK) of curcumol in patients with COVID-19 and LUAD." (PMID 35520289, 2022). "The molecular network analysis using Cytoscape highlighted seven core targets of curcumol, namely, AURKA, CDK1, CCNB1, CCNB2, CCNE1, CCNE2, and TTK in COVID-19 and LUAD." (PMID 35520289, 2022). "We identified seven core pharmacological targets of curcumol, namely, AURKA, CDK1, CCNB1, CCNB2, CCNE1, CCNE2, and TTK, in treating LUAD and COVID-19." (PMID 35520289, 2022).
cyst (3 papers, 2015 to 2025). A sac-like closed membranous structure that may be empty or contain fluid or amorphous material. "By P21 AURKA expression was limited to a rare collecting duct cells in wild-type mice, but cyst development was associated with an increase in cells expressing AURKA." (PMID 38191531, 2024). "Consistent with previous studies of ADPKD models, we find that treatment with the AURKA kinase inhibitor Alisertib increases cyst number in JS mice and that this is linked to an unexpected accumulation of AURKA following drug treatment and AKT activation." (PMID 38191531, 2024). "Cross-comparison of transcriptional changes implicated AKT signaling in cyst prevention and we show that (i) AURKA and AKT physically interact, (ii) AURKA regulates AKT activity in a kinase-independent manner and (iii) inhibition of AKT can reduce disease severity." (PMID 38191531, 2024). "We next examined whether AURKA also contributes to cyst development in ADPKD downstream of POLYCYSTIN mutations." (PMID 38191531, 2024). "Better understanding the direct and indirect mechanistic effects of AURKA on these cyst promoting pathways will be critical to understanding it’s central role in disease progression." (PMID 38191531, 2024). "Despite evidence supporting a role for AURKA in promoting cyst development, its inhibition using Alisertib instead exaggerates ADPKD in mouse models." (PMID 38191531, 2024). "After allowing significant cyst development in this model, we then deleted AURKA at 4 weeks (P28) of age using the Dox system previously employed to study late onset disease, ageing mice to 26 weeks (6 months) of age." (PMID 38191531, 2024). "Collectively, these findings indicate that AURKA is a master regulator of both the polycystin-mediated (major) and syndromic (minor; JS) pathways that drive cyst development in different types of PKD." (PMID 38191531, 2024). "Previous studies have examined the role of AURKA in cyst development using Alisertib (MLN8237), an AURKA kinase inhibitor which blocks ATP binding and prevents T288 phosphorylation." (PMID 38191531, 2024). "Using different mouse models of Polycystic Kidney Disease, this research demonstrated that deletion of the Aurora Kinase A gene was able to prevent cyst initiation and growth, identifying it as a central regulator of pathogenesis in this condition." (PMID 38191531, 2024). "Conditional deletion of Aurka in Pkd1∆/∆ mice (confirmed by reduction in AURKA expression) resulted in an almost complete suppression of cyst formation." (PMID 38191531, 2024). "Nonetheless, the identification of a shared AURKA-AKT-mediated cyst promoting axis which underpins disease development in different types of PKD provides important molecular insights into renal cyst formation." (PMID 38191531, 2024). "As well as preventing cyst formation, our experiments examining Aurka deletion in existing cysts suggests an ongoing role for AURKA in cyst growth." (PMID 38191531, 2024). "In RC mice we speculate the mild nature of the disease along with different cellular dependencies on AURKA with respect to cyst initiation and progression may explain why haploinsufficiency did not afford benefit." (PMID 38191531, 2024). "Given the pleiotropic role that AURKA plays in many aspects of cellular homoeostasis the protein may also regulate cyst development via pathways other than AKT." (PMID 38191531, 2024). "Deletion of AURKA in mouse models of autosomal dominant PKD and Joubert Syndrome reduces cyst formation and the disease severity of PKD, in part via modulating AKT signalling in the kidney." (PMID 40247090, 2025). "In the current study, to probe these novel actions of AURKA in ADPKD, we have evaluated the interaction of the EGFR inhibitor erlotinib with alisertib in control of cyst formation." (PMID 26528438, 2015).
cyst (continued). "In contrast, Inpp5eΔ/Δ;AurkaΔ/Δ Alisertib-treated mice displayed no change in kidney-to-body-weight ratio, cyst index, cyst number or cyst size, confirming Alisertib requires AURKA (and not AURKB or other targets) to elicit these pro-cystogenic effects." (PMID 38191531, 2024). "With regards to the mechanism by which AURKA might regulate AKT activity during cyst development, we provide evidence that AURKA interacts with AKT in the testis and cystic (but not healthy) kidneys, and that AURKA regulates AKT phosphorylation, independent of its kinase activity." (PMID 38191531, 2024).
diabetes (3 papers, 2020 to 2023). "Here, we sought to confirm the change of AURKA expression under a mimicked diabetes and ischemia-induced tissue starvation environment in vivo." (PMID 36977984, 2023). "Thirdly, our studies support the role of AURKA as a critical angiogenic factor in diabetes-related limb ischemia, and preliminary explored the possible involvement of VEGFR2/PI3K/AKT pathway." (PMID 36977984, 2023). "The in vivo function of AURKA in post-ischemic angiogenesis related to diabetes was verified in our murine model of diabetic limb ischemia, and the results were consistent with in vitro experiments." (PMID 36977984, 2023). "Research has reported that the enhanced healing and/or regenerative capacity after ischemia is attributed to increased capillary and arterial vascular density in the ischemic limb, and the potential role of AURKA in wound repair has been hinted in diabetes." (PMID 36977984, 2023). "In conclusion, our research improved that AURKA plays an important regulatory role in post-ischemic angiogenesis related to diabetes via the promotion of endothelial proliferation and oxidative stress response." (PMID 36977984, 2023). "Endoplasmic reticulum stress-induced autophagy deficiency is associated with chronic inflammation observed in patients with diabetes, AURKA via Targeting FOXO3a enhanced autophagy of Adipose-Derived Stem Cells (ADSC).promote DW healing." (PMID 33967796, 2021). "Based on these observations, we might conclude that AURKA plays a potent role in blood flow recovery under diabetes and ischemia." (PMID 36977984, 2023). "Moreover, AURKA overexpression rescued diabetes-related impairment of angiogenesis, arteriogenesis, and functional recovery in the ischemic limb." (PMID 36977984, 2023). "In cancer and diabetes, AURKA has been demonstrated to function in glucose metabolism, suggesting that AURKA might promote the high glucose metabolism in microvascular endothelial cells to relieve VEGFA resistance." (PMID 36977984, 2023). "In addition to its role in angiogenesis, in diabetes, AURKA inhibits high glucose-induced stem cell apoptosis and promotes repair of damaged skin repair in diabetic mice." (PMID 36977984, 2023). "Thus, we proposed that AURKA might stimulate microvascular endothelial cells to form a vascular network via two distinct mechanisms: induction of VEGFA expression in diabetes-related limb ischemia and increased sensitivity of endothelial cells to VEGFA." (PMID 36977984, 2023). "Next, we explored whether AURKA could exert its beneficial effect in the HLI model with diabetes." (PMID 36977984, 2023). "Thus, AURKA might be considered as a contributor to protect against diabetes-related limb ischemia for its critical role in promoting angiogenesis and salvaging ischemic tissues." (PMID 36977984, 2023). "In our study, the in vitro and in vivo findings revealed the essential role of AURKA in regulating the angiogenic potential of microvascular endothelial cells under physiological and pathological conditions and the angiogenesis under post-diabetic ischemia conditions." (PMID 36977984, 2023).
endometrioid ovarian carcinoma (3 papers, 2021 to 2023). "Overexpression of AURKA was an unfavorable prognostic factor in endometrioid ovarian cancer and UCEC36,37." (PMID 37803076, 2023).
esophageal adenocarcinoma (3 papers, 2022 to 2025). A malignant tumor with glandular differentiation arising predominantly from Barrett mucosa in the lower third of the esophagus. "We report that Aurora kinase A (AURKA) promotes cancer cell survival by activating UPR in esophageal adenocarcinoma (EAC)." (PMID 35326553, 2022). "Our data using both in vitro cancer cell models and in vivo mice models discovered, for the first time, that Aurora kinase A hijacks pro-survival unfolded protein response in esophageal adenocarcinoma, promoting the survival of cancer cells under reflux-mediated stress conditions." (PMID 35326553, 2022). "The analysis demonstrated a significant positive correlation of AURKA mRNA and BIP mRNA expression in esophageal tissue samples (p < 0.0001, 11 normal esophagus samples, 79 esophageal adenocarcinoma samples)." (PMID 35326553, 2022).
gastrointestinal stromal tumor (3 papers, 2014 to 2024). "Our previous studies revealed that AURKA overexpression predicts recurrence in patients with primary, surgically resected, gastrointestinal stromal tumors (GISTs)." (PMID 24901229, 2014). "In the study on gastrointestinal stromal tumors (GISTs), CSTF1 was involved in a fusion with Aurora kinase A (AURKA)." (PMID 39185313, 2024).
laryngeal carcinoma (3 papers, 2016 to 2019). Carcinoma that arises from the laryngeal epithelium. "Moreover, the mitotic kinase Aurora-A (AURKA) is also highly expressed in the nucleus of breast CSCs, and promotes sphere formation, radioresistance, invasion, and metastasis in breast and laryngeal cancer cells." (PMID 30800215, 2019). "We conclude that AURKA may revive dormant tumor cells via FAK/PI3K/Akt pathway activation, thereby promoting migration and invasion in laryngeal cancer." (PMID 27356739, 2016). "Western blotting revealed that AURKA expression was persistently low in dormant laryngeal cancer Hep2 (D-Hep2) cells and high in non-dormant (T-Hep2) cells." (PMID 27356739, 2016). "In conclusion, we demonstrated that AURKA may revive dormant tumor cells via FAK/PI3K/Akt pathway activation, thereby promoting migration and invasion in laryngeal cancer." (PMID 27356739, 2016).
laryngeal squamous cell carcinoma (3 papers, 2016 to 2019). A squamous cell carcinoma that arises from the larynx. "Aurora kinase A (AURKA) has been implicated in numerous types of cancer and reported to promotes cell migration & invasion tumor progression in patients with laryngeal squamous cell carcinoma (LSCC)." (PMID 31692905, 2019). "We hypothesized that aurora kinase A (AURKA), a cell cycle control kinase, promotes the transition of laryngeal squamous cell carcinoma (LSCC) cells from G0 phase to active division." (PMID 27356739, 2016).
maturity onset diabetes (3 papers, 2008 to 2022). "Also, cytosolic DNA sensing pathway, graft versus host disease, maturity onset diabetes of the young, olfactory transduction, and regulation of autophagy exhibited positive correlations to AURKA." (PMID 36506308, 2022).
meningioma (3 papers, 2016 to 2025). A generally slow growing tumor attached to the dura mater. "PTK2B (inhibitor: defactinib) was upregulated in merlin-deficient schwannoma cells by Panobinostat and AURKA (inhibitor: alisertib) was upregulated in merlin-deficient meningioma upon treatment with GSK2126458 and CUDC-907." (PMID 29897904, 2018). "A case in point was AURKA, which was identified as a suppressor of erastin‐induced ferroptosis in meningioma." (PMID 40982354, 2025). "Suppression of AURKA in combination with erastin improved prognosis in a meningioma mouse model." (PMID 40982354, 2025).
mucositis (3 papers, 2023). Mucositis is inflammation and damage of the mucous membranes lining the mouth and other parts of the gastrointestinal (GI) tract. "Suppression of AURKA induces sensitivity to everolimus by inducing cell death in vivo, again confirming the close association between the mTORC1 pathway and AURKA, suggesting that AURKA plays an important role during the development of mucositis." (PMID 36902486, 2023).
renal carcinoma (3 papers, 2012 to 2022). A carcinoma arising from the epithelium of the renal parenchyma or the renal pelvis. "AURKA activates the vacuolar H+-ATPase (V-ATPase) in Caki-2 cells, a human kidney carcinoma cell line." (PMID 35054947, 2022). "Dysregulation of AURKA has been found in numerous cancers, including lung, cervical, and renal cancers, showing that it can facilitate cell growth and invasion, but represses cell apoptosis." (PMID 34702201, 2021).
renal cell carcinoma (3 papers, 2009 to 2021). "Next, a panel of VHL-null renal cell carcinoma (RCC) cell lines with elevated AURKA expression were used to determine if NVP-BEZ235 treatment decreased AURKA expression." (PMID 34002003, 2021).